RBPJ (recombination signal binding protein for immunoglobulin kappa J region)
Diseases named in the same sentence as RBPJ in open-access papers (continued):
Sharing a sentence is not in itself a finding about the gene and the disease.
oligodendroglioma (1 paper, 2018). A well-differentiated (WHO grade II), diffusely infiltrating neuroglial tumor, typically located in the cerebral hemispheres. "Recombinant signal binding protein for immunoglobulin kappa-J region (RBPJ), the nuclear binding partner of activated NOTCH1’s intracellular binding domain (NICD), was mutated (n = 5) or homodeleted (n = 1) in 3% (6 of 169) of oligodendrogliomas." (PMID 30417117, 2018). "Thus, RBPJ mutation likely represents an alternative mechanism for Notch pathway inactivation in oligodendroglioma." (PMID 30417117, 2018).
osteosclerosis (1 paper, 2022). Abnormally high bone density. "RBPJ in osteoblasts has not only been shown to inhibit osteogenesis, but this has been shown to prevent osteosclerosis from developing in RBPJ- knockout mice." (PMID 35806237, 2022).
rectal cancer (1 paper, 2021). A primary or metastatic malignant neoplasm that affects the rectum. "Thus, as a consequence of inflammatory STAT3 signaling NICD and RBPJ form a functional transcription factor complex in CRT-resistant rectal cancer cells." (PMID 33530306, 2021). "Mechanistically, phospho-STAT3 executed CRT resistance in rectal cancer cells by supporting NOTCH signaling, specifically by stimulating expression of RBPJ, the key transcriptional effector of the NOTCH pathway." (PMID 33530306, 2021). "Importantly, when RBPJ expression was silenced in otherwise CRT-resistant SW837 rectal cancer cells, the cells were re-sensitized to CRT, showing that RBPJ—like STAT3—is a key determinant of CRT resistance." (PMID 33530306, 2021). "We furthermore show that preventing RBPJ/NICD complex formation re-sensitized CRT-refractory tumor cells and thus offers a promising therapeutic strategy to solve the problems that come along with CRT resistance in rectal cancer." (PMID 33530306, 2021).
rhabdomyosarcoma (1 paper, 2012). A rare aggressive malignant mesenchymal neoplasm arising from skeletal muscle. "In this study, we focused on the role of RBPJ in the pathogenesis of rhabdomyosarcoma (RMS)." (PMID 22792167, 2012).
Sepsis (1 paper, 2022). Sepsis is defined as life-threatening organ dysfunction caused by a dysregulated host response to infection. "Furthermore, we analyzed the downstream TFs targeted by LR pairs and found that different TFs, including SMAD3, RBPJ, and MAX, were targeted in sepsis-only patients, while FOS, STAT3, STAT2, and RB1 were targeted in sepsis-induced patients." (PMID 35222683, 2022).
type 1 diabetes (1 paper, 2023). "Among these genes, five (IL6R, RBPJ, SKAP2, SIRPG, UBASH3A) harbour a nearby type 1 diabetes-associated SNP." (PMID 37224769, 2023).
tumor (75 papers, 2009 to 2025). "Loss of RBPJ leads to activation of dermal fibroblasts and promotes their transformation into cancer-associated fibroblasts (CAFs), which play a crucial role in tumor development and growth." (PMID 34433485, 2021). "In tumor stromal cells, loss of RBPj has been shown to promote fibroblast activation and conversion into CAFs and ensures keratinocyte-derived tumors." (PMID 32616053, 2020). "Evaluation of tumor metastasis revealed that RBPj deficiency in SM22-MCs promoted lung metastasis of subcutaneous LLC tumors." (PMID 32616053, 2020). "As previously observed for early phase, RBPJ-deficient conditions allowed a better control of tumor growth until 10 days." (PMID 29930552, 2018). "T cells transferred resulted in the control of RBPJ-deficient mice tumor growth similar to that in Notch-competent mice." (PMID 29930552, 2018). "Three weeks after subcutaneous injection of Hepa1–6 cells, the area of the tumor was significantly increased in RBPJ-deficient mice compared with control mice." (PMID 29930552, 2018). "We showed that even if T cells secreting GzmB, TNFa, and IFNg were more numerous the cytotoxicity produced by cNK populations against the tumor was higher in RBPJ-deficient mice, even after T cell transfer." (PMID 29930552, 2018). "The analysis of the tumor-infiltrating cells indicated that CD49a+ CD49b+ cNK subset was only found in RBPJ-deficient animals that were more efficient than the conventional cNK subset in secreting GzmB and TNFa." (PMID 29930552, 2018). "Our results indicate that RBPJ+/+ Mφ-Exo may have potential in the regulation of tumor proliferation and hsa_circ_0004658 could be a diagnostic biomarker and potential target for HCC therapy." (PMID 35013102, 2022). "Therefore, the tumor area difference between RBPJ-competent and -deficient mice starts around day 14 post-injection." (PMID 29930552, 2018). "Finally, we showed that RBPJ deficiency also increased the control of tumor proliferation at the early time-points due to the recruitment of highly inflammatory cNK cells." (PMID 29930552, 2018). "Because RBPJ-deficient controlled better than RBPJ-competent mice the expansion of the tumor at early time points, we analyzed the type 1 ILC composition and functions 5 days after tumor injection, a time point at which no infiltrating T cells could be detected." (PMID 29930552, 2018). "MYC overexpression canceled Notch activation-induced proliferation arrest of TECs in vitro, and a MYC inhibitor normalized tumor vessels in RBPj deficient mice, suggesting that MYC is the authentic Notch target in normalizing tumor vessels." (PMID 40303332, 2025). "Immunohistochemistry (IHC) analysis revealed increased RBPJ protein levels in 90% of tumor tissues compared with adjacent tissues." (PMID 40289107, 2025). "The results revealed that, although the 10058-F4 treatment did not impact tumor growth, it markedly abolished the phenotype of enhanced tumor necrosis and hypoxia in RBPj knockout mice." (PMID 40303332, 2025). "We also confirmed that HES1 levels were regulated in an RBPJ-dependent manner on treatment with tumor conditioned media from B16F10 or TC-1." (PMID 39702544, 2024). "The results of the IHC assay confirmed that the level of RBPJ was markedly elevated in PC tissues compared with that in adjacent non-tumor tissues." (PMID 39725730, 2024). "Triptonide, a natural small molecule extracted from Tripterygium wilfordii Hook F, efficiently inhibits tumor growth and metastasis via decreasing the levels of Notch1 downstream proteins RBPJ, IKK alpha, IKK beta, reducing p52 phosphorylation." (PMID 39092224, 2024). "On treatment with tumor-CM, enhanced luciferase activity was seen for the promoter sequence of Hes1 with the RBPJ consensus binding motif." (PMID 39702544, 2024).
tumor (continued). "There is feasible evidence that RBPJ plays an essential for DCs to evoke efficient anti-tumor immune response through affecting series of processes including maturation, migration, antigen presentation, and T cell activation." (PMID 37957143, 2023). "The simultaneous change of RBPJ with T cell exhaustion mean that it was an important regulator of tumor infiltrating CD8+ T cells." (PMID 36717584, 2023). "In accordance with in vitro results, the levels of Hes5 proteins in tumor tissues were considerably decreased after mice received various doses of fidaxomicin, suggesting a possible RBPJ-dependent inhibitory mechanism of action." (PMID 35631382, 2022). "The greatest difference in the tumor volume was between tumors of SMMC-7721 cells cocultured with RBPJ+/+ Mφ-Exo and those transfected with sh-circRNA, whereas sh-circRNA tumors were significantly larger." (PMID 35013102, 2022). "Blocking Notch signaling or RBPJ reduced clonogenic potential in tumor-sphere assays and engraftment capacity in GBM xenograft models." (PMID 36627893, 2022). "IRF8 was associated with depleted CD8+ T cells in the GC.The transcription factor RBPJ was overexpressed in the tumor-infiltrating Tregs.DC cells expressed more inhibitory receptors in GC tissues, for example, FTL and IL8." (PMID 35785171, 2022). "Exo-LBX1-AS1 secreted from RBPJ-OE Mφ inhibits tumor progression through the LBX1-AS1/miR-182-5p/FOXO3 pathway, and LBX1-AS1 is probably a diagnostic biomarker and potential target for OSCC therapy." (PMID 33816238, 2021). "The mandatory RBPJ interaction partner, NOTCH intracellular domain, was provided by tumor cell-intrinsic expression of NOTCH ligands that caused tonic NOTCH proteolysis." (PMID 33530306, 2021). "The greatest differences in the tumor volume and weight were observed in the tumors between RBPJ-OE Mφ-Exos group and sh-lncRNA group." (PMID 33816238, 2021). "What’s more, the inhibitory effects of RBPJ-OE Mφ-Exos on the tumor growth in vivo were eliminated when LBX1-AS1 was knocked down in Exos." (PMID 33816238, 2021). "Tumor-infiltrating cells were analyzed revealing a lower frequency of T cells and conversely a higher frequency of type 1 ILC in RBPJ-deficient mice compared with controls." (PMID 29930552, 2018). "Tumor vessels, which were aggravated by RBPj deficiency, were normalized significantly by 10058-F4 as shown by reduced vessel density, increased mural coverage and vessel perfusion." (PMID 40303332, 2025). "By integrating analysis of CUT&Tag and RNA sequencing data, we identified ubiquitin-specific protease 5 (USP5) as a Notch-signaling downstream effector that is transcriptionally upregulated by the NOTCH1 intracellular domain (NICD1)–RBPJ complex and mediates tumor angiogenesis." (PMID 40691441, 2025). "In UCEC, RBPJ exerts a tumor suppressor role by inhibiting cell malignant behaviors." (PMID 39901144, 2025). "Furthermore, HCC cells co-cultured with macrophage exosomes targeting RBPJ exhibited increased tumor proliferation and body weight following subcutaneous injection into nude mice." (PMID 41299506, 2025). "Subsequently, NICD can bind to the RBPJ and influence tumor development." (PMID 38733531, 2024). "Functionally, although both SPEN deficiency and RBPJ deficiency inhibit tumor growth, SPEN deficiency normalizes while RBPJ deficiency disrupts tumor vasculature, and disruption of both leads to normalized tumor vessels." (PMID 37607001, 2023). "Moreover, RBPJ+/+ Mφ-Exo inhibits tumor growth by upregulating the hsa_circ_0004658/miR-499b-5p/JAM3 pathway in vivo." (PMID 35013102, 2022). "Nevertheless, the connection between changed RBPJ gene dosage and tumorigenesis is multifaceted and may diverge depending on the tumor type." (PMID 36627893, 2022). "In vivo assays further verified that RBPJ-OE Mφ-Exos might inhibit tumor growth through a LBX1-AS1/miR-182-5p/FOXO3 pathway in xenograft tumor models." (PMID 33816238, 2021).
tumor (continued). "Moreover, RBPJ-OE Mφ-Exos inhibits tumor growth by stimulating the LBX1-AS1/miR-182-5p/FOXO3 pathway in vitro and in vivo." (PMID 33816238, 2021). "Interestingly, we found that the transcription factor RBPJ was overexpressed in tumor-infiltrate Tregs." (PMID 32039830, 2020). "The tumor lines had comparable levels of RBPJ protein; therefore, the varying effects of RIN1 on tumor cell proliferation might reflect differential reliance on RBPJ-dependent versus RBPJ-independent NOTCH signaling." (PMID 31346210, 2019). "RBPJ is a primary transcription mediator of canonical Notch signaling, which participates in cell fate determination, and is involved in the regulation of tumor behavior in multiple decisions." (PMID 23181716, 2012). "Additionally, RBPJ expression was significantly correlated with tumor stage." (PMID 40289107, 2025). "Combined with in vitro cytotoxicity and qRT-PCR results, these findings implied that fidaxomicin might effectively block the formation of the RBPJ-dependent transcriptional complex, leading to the inhibitory ability on Notch signaling and resulting in anti-tumor activity." (PMID 35631382, 2022). "PPI analysis indicated that the levels of the mRNAs encoding RBPJ, SKP1, CTNNB1, CDH2, SCG2, VGF, and TFF3 were significantly increased in PanNEN tumor tissues compared with the matched paratumor tissues and may be involved in the DNER signaling pathway in PanNENs." (PMID 33329729, 2020). "In addition, we found that another transcription factor, RBPJ, was overexpressed in tumor-infiltrate Tregs and might regulate the LAG3." (PMID 32039830, 2020). "Moreover, at 21 days post-transplantation, RBPJ-deficient mice showed no sign of tumor rejection while 50% of control mice were tumor free." (PMID 29930552, 2018). "KO of RBPJ in T cells increases IRF1 expression, with enhanced effector functions and tumor control." (PMID 40693464, 2025). "Deletion of RBPJ in both OT-1 cells and anti-hCD19 CAR-T cells enhanced proliferation and effector functions in several tumor models." (PMID 40693464, 2025). "RBPJ was shown to promote GBM cell proliferation, invasion, stemness, and tumor initiation via enhancing activation of the IL-6-STAT3 pathway and proneural-mesenchymal transition (PMT)." (PMID 38971772, 2024). "Regulation of HES1 expression by RBPJ was also observed in a human macrophage cell line, THP-1 cells, on treatment with tumor conditioned media from AGS or MB231." (PMID 39702544, 2024). "To establish the functional relationship between RBPJ and IRF1, we transferred OT-I cells transduced with sgNTC, sgRbpj, sgIrf1 or sgRbpj with sgIrf1 into B16-OVA tumour-bearing mice." (PMID 37968405, 2023). "Results showed that the high value of regulatory potential between MFAP5 and some of its top predicted NOTCH1/WNT pathway target genes (CCND1, HES1, MYC, RBPJ, NOTCH1, CCN3, CTNNB1 and SOX17) in inferring signaling paths in tumour tissues." (PMID 36855786, 2023). "The hot genes with the most positive signal events in the normal-specific group were RBPJ, PFKFB3, CAMK1D, ACACB, and WWOX, whereas the hot genes in the tumor-specific group were SLC35F3, PCDH7, NF1, and RAB27B." (PMID 36895481, 2023). "In tumor cells, c-MYC directly activates RBPJκ and subsequent target genes in a NOTCH activation-independent manner, mediated by CDK9, a component of positive transcription elongation factor b (P-TEFb)." (PMID 35215234, 2022). "Furthermore, due to the nuclear location of the RBPJ protein, the intracellular trafficking behavior of fidaxomicin implied that this compound might inhibit the formation of the RBPJ complex, hence blocking the Notch signal pathway and eventually exerting the potential anti-tumor ability." (PMID 35631382, 2022). "An active heterodimeric NOTCH effector complex, called RBPJ/NICD, was assembled in CRT-resistant tumor cells as a result of tonic signal input from two separate signaling cascades." (PMID 33530306, 2021).
tumor (continued). "In tumor-infiltrate Tregs, we found that IFIT2, CCL3, RBPJ, etc. were upregulated in GC tissues compared to adjacent normal tissues while IGJ, XCL1, XCL2, etc. were downregulated." (PMID 32039830, 2020). "DNER regulates its downstream target RBPJ and SKP1, and also interacts with the important factors of Wnt signaling pathways, CTNNB1 and CDH2, regulating tumor proliferation, differentiation, invasion, migration and angiogenesis of PanNENs tumorigenesis." (PMID 33329729, 2020). "We also found strong nuclear positivity of RBPJ and SKP1 in tumor tissue compared with paratumor tissue, with significant differences (P < 0.05)." (PMID 33329729, 2020). "RIN1 showed a stronger inhibitory effect on tumor growth than Hepa1-6Rbpj-KD, which suggested that RIN1 inhibition of tumor growth did not rely solely on blocking the assembly of RBPJ transcription complex in tumor cells." (PMID 36717584, 2023). "RBPJ+/+ Mφ-Exo and hsa_circ_0004658 inhibits proliferation and promotes apoptosis in HCC cells, whereas hsa_circ_0004658 knockdown stimulated cell proliferation and migration but restrained apoptosis in vitro and promotes tumor growth in vivo." (PMID 35013102, 2022). "We found RBPJ to be a direct target gene of signaling active STAT3, which may explain these observations together with the tumor cell-autonomous processing of NOTCH leading to NICD production and the assembly of the transcriptionally active RBPJ/NICD complex." (PMID 33530306, 2021). "Confirming our previous data, we found that in tumors with M1hot TAMs compared with M1cold TAMs, the tumor-infiltrating CD8+ T cells showed increased expression of genes strongly enriched for TRM signature genes (eg, ITGAE, RBPJ) in addition to cell cycle and cytotoxic/cytokine signature genes." (PMID 32699181, 2020). "We then quantified the expression of DNER, RBPJ, SKP1, CTNNB1, and CDH2 in solid tumor and paratumor paraffin sections by immunohistochemistry and found strong cytoplasmic positivity of DNER in tumor tissue compared with paratumor tissue, with significant differences (P < 0.05)." (PMID 33329729, 2020). "To recover enough immune cells from the tumor, we did not extend our analysis over 2 weeks and observed that even after T cell transfer, type 1 ILC were more frequent and more cytotoxic in RBPJ-deficient animals." (PMID 29930552, 2018). "However, treatment with RIN-1, an inhibitor of the RBPJ subunit of the NOTCH complex, significantly decreased SOX2 expression in tumor cells, suggesting that SOX2 expression regulated by NOTCH signaling may contribute to tumor development." (PMID 40128799, 2025). "In the tumors overexpressing RBPJ+/+ Mφ-Exo tumors were significantly smaller than all other tumors, therefore the upregulation of hsa_circ_0004658, which leads to the downregulation of miR-499b-5p and the upregulation of JAM3, results in a tumor-suppressive phenotype in the mouse HCC model." (PMID 35013102, 2022).